ALB (albumin)
Diseases named in the same sentence as ALB in open-access papers (continued):
Sharing a sentence is not in itself a finding about the gene and the disease.
pneumonitis (6 papers, 2020 to 2025). An inflammatory process affecting the lung parenchyma. "Importantly, high IL-6 or low ALB levels could be applied to improve risk stratification in pneumonitis." (PMID 34327140, 2021). "High levels of IL-6 and low concentrations of ALB at the time of initial onset of CIP symptoms were predictive of severe pneumonitis." (PMID 34327140, 2021). "In the multivariate analysis, high ALB levels were negatively correlated with severe pneumonitis (OR: 0.16, 95% CI: 0.04–0.64)." (PMID 34327140, 2021). "High IL-6 levels (OR: 5.23, 95% confidence interval [CI]: 1.15–23.86; p = 0.033), and low levels of ALB (OR: 0.16, 95% CI: 0.04–0.64; p = 0.009) measured at the time of CIP symptom onset were associated with severe pneumonitis." (PMID 34327140, 2021). "Cytokines, blood routine, lactate dehydrogenase (LDH) and albumin (ALB) were collected at baseline (before ICIs), at onset of pneumonitis (in the CIP group), and before the last dose of ICI (in the control group)." (PMID 34327140, 2021). "Univariate analysis indicated that age, IIPs, PD‐L1, WBC count, eosinophil count, monocyte count, and albumin and C‐reactive protein (CRP) levels were risk factors for ICI pneumonitis." (PMID 33201587, 2021). "By contrast, high concentrations of ALC and ALB were negatively correlated with severe pneumonitis." (PMID 34327140, 2021). "To evaluate our hypothesis, we first labeled albumin with Cy7 and used 3D OI/CT to evaluate its distribution in a mouse model of LPS-induced pneumonitis compared to controls." (PMID 34766000, 2020). "Clinical characteristics and biomarkers, such as serum CRP, PCT, and albumin levels measured during the first 24 h, were not useful to differentiate BAP from pneumonitis." (PMID 36431150, 2022).
Respiratory tract infection (6 papers, 2020 to 2025). An infection of the upper or lower respiratory tract. "Patients in the ECMO group had lower albumin and creatinine levels than controls, higher rates of directed antibiotic therapy for respiratory tract infections or bacteraemia, and a greater likelihood of MV." (PMID 41009917, 2025). "It is also worth noting that the putative effect of low albumin levels, resulting in increased interstitial lung fluid and decreased lung clearance is another factor contributing to potential respiratory tract infections." (PMID 33292553, 2020).
spinal tuberculosis (6 papers, 2022 to 2024). "There was a potential risk of cerebrospinal fluid leakage and reduced albumin after surgery for spinal tuberculosis." (PMID 35425806, 2022). "Using this scale, patients with spinal tuberculosis were divided into a high-risk group and a low-risk group, and then, calculated the average decrease of postoperative albumin in both groups." (PMID 35571899, 2022). "Nutritional status is also a vital factor affecting the progression and prognosis of spinal tuberculosis patients, and research has shown that the serum ALB concentration is an important laboratory marker for predicting SCI and prognosis in STB patients." (PMID 38565845, 2024). "Multivariate logistic regression analysis found that albumin quantity could be an independent factor for predicting post-operative complications of spinal tuberculosis." (PMID 35425806, 2022). "The albumin quantity may be an independent factor to predict post-operative complications of spinal tuberculosis by logistic regression analysis." (PMID 35425806, 2022).
squamous non-small cell lung cancer (6 papers, 2022 to 2025). "In conclusion, the nanoparticle albumin-bound paclitaxel + carboplatin + bevacizumab combination is favorable and well tolerated in Japanese patients as first-line treatment for advanced non-squamous non-small cell lung cancer." (PMID 38594880, 2024). "The combination of the nanoparticle albumin-bound paclitaxel + carboplatin + bevacizumab as first-line treatment for advanced non-squamous non-small cell lung cancer is revealed to be favorable and well tolerated in Japanese patients." (PMID 38594880, 2024).
stomach cancer (6 papers, 2016 to 2021). "Similarly, there are many studies reporting the preoperative albumin values between 3.0 and 3.9 g/dl in patients with gastric tumors." (PMID 31827513, 2019).
thyrotoxicosis (6 papers, 2021 to 2025). A hypermetabolic syndrome caused by the elevation of thyroid hormone levels in the serum. "In harmony with previous studies, the current results elicited that thyrotoxicosis augmented the activities of both ALT and AST along with a sharp decrease in the levels of total protein, albumin and globulin." (PMID 38303002, 2024). "Severe thyrotoxicosis can increase SHBG levels and slightly decrease albumin levels." (PMID 39901894, 2025).
vascular dementia (6 papers, 2007 to 2022). A degenerative vascular disorder affecting the brain. "Deamidation products of blood albumin were significantly elevated in vascular dementia and frontotemporal dementia (P < 0.05), but less so in PD." (PMID 36575499, 2022). "Elevated albumin and other serum proteins have been found in CSF and in the brain of patients with vascular dementia." (PMID 25147945, 2014). "Typically, the CSF/serum albumin ratio is normal in patients with pure AD, whereas patients with vascular dementia generally present with elevated albumin ratio." (PMID 21487447, 2010). "Elevated CSF and serum albumin that reflect albumin extravasation and BBB leakage have been found in patients with vascular dementia." (PMID 36119691, 2022). "Increased albumin CSF/serum ratio, a marker of BBB breakdown, has also been reported in patients with vascular dementia and WMH on neuroimaging." (PMID 36119691, 2022).
abdominal abscess (5 papers, 2016 to 2025). An abscess located in the abdominal cavity, i.e., the cavity between the diaphragm above and the pelvis below. "The independent risk factors for late PPH included postoperative pancreatic fistula postoperative bile fistula postoperative abdominal abscess revascularization, history of abdominal surgery, and preoperative albumin levels." (PMID 27975049, 2016). "The inhibitory effects of increased cortisol and endotoxin levels on albumin synthesis observed in animal models or patients with abdominal abscess may have contributed to this finding." (PMID 34920728, 2021).
abdominal aortic aneurysm (5 papers, 2013 to 2024). Enlargement and ballooning of the vessel that supplies arterial blood to the abdomen, pelvis and legs. "In the European guideline for abdominal aortic aneurysms it is recommended to measure serum albumin to assess the nutritional status of the patient." (PMID 35862384, 2022). "The association between abdominal aortic aneurysms and inflammation is previously studied and some markers such as white blood cell (WBC), C-reactive protein (CRP), interleukin 6, and albumin are shown to be responsible." (PMID 36195877, 2022). "The CRP-to-albumin ratio (CAR) was found a better indicator of the inflammatory process than either marker alone in cardiovascular disease development and also the progression of abdominal aortic aneurysms." (PMID 36195877, 2022).
acute cholangitis (5 papers, 2019 to 2024). Cholangitis that is both sudden in onset and of a relatively short duration. "The platelet, PT-INR, creatinine, and albumin levels were significantly different, according to the severity of acute cholangitis." (PMID 35208579, 2022). "Laboratory data at the time of admission revealed worse platelet count (p = 0.013), total bilirubin (p < 0.001), aspartate transaminase (p < 0.001), albumin (p = 0.001), and alanine transaminase (p < 0.001) levels in the concomitant biliary infections group than in the non-acute cholangitis group." (PMID 30581570, 2019). "The severity assessment of acute cholangitis in TG18 also took into account factors such as fever, white blood cell count, age, bilirubin, and serum albumin." (PMID 37599814, 2023).
acute GVHD (5 papers, 2013 to 2024). "Using an optimal protocol, dissolving DSCs in albumin, 21 patients with severe acute GVHD, all responded with a 1-year survival of 81%." (PMID 38204331, 2024). "At the Karolinska Institute, severe acute GVHD patients treated with placenta-derived DSCs supplemented with either 5% albumin or 10% AB plasma displayed a one-year survival rate of 76% and 47% respectively." (PMID 37868964, 2023). "Three weeks after day 0, albumin levels were significantly higher in the acute GVHD group treated with DSCs than in the acute GVHD-control group (p = 0.03)." (PMID 28744284, 2017). "Furthermore, patients with steroid-refractory acute GVHD, displayed survival rates of 73% with albumin and 31% with AB plasma-supplemented DSCs, compared to the 20% survival rate in the mesenchymal stromal cell control group." (PMID 37868964, 2023).
Acute hepatitis (5 papers, 2013 to 2026). Acute hepatic injury resulting from inflammation typically accompanied by increased serum alanine transaminase activity. "The best-defined grade of liver impairment is “severe”, which is defined in multiple SmPCs/PI by a Child–Pugh score C, serum albumin level, and an example of a disease (acute hepatitis), as well as defined symptoms (coma/precoma hepaticum)." (PMID 35407541, 2022). "Vitamin D inhibits virus replication; it has an effective role in platelet and albumin levels and reducing ALT enzyme levels in patients with acute hepatitis." (PMID 36411916, 2022).
acute lymphoblastic leukemia (5 papers, 2021 to 2025). Leukemia with an acute onset, characterized by the presence of lymphoblasts in the bone marrow and the peripheral blood. "The aim of our study was to establish alterations of nutritional status in 26 children and adolescents treated for acute lymphoblastic leukemia (ALL) at the Children’s Hospital in Zagreb, Croatia, between 2016 and 2021, by using anthropometric measures and serum albumin levels." (PMID 38539369, 2024). "ALB and TNF may serve as potential biomarkers for the diagnosis and treatment of acute lymphoblastic leukemia in children with MLL gene rearrangements." (PMID 41293238, 2025).
aortic aneurysm (5 papers, 2014 to 2025). A ruptured aneurysm located in the wall of the proximal portion of the descending aorta proceeding from the arch of the aorta. "This study investigated whether preoperative serum albumin levels could be used to predict mortality in patients with aortic aneurysms undergoing graft replacement of ascending aorta and aortic arch." (PMID 37082727, 2023). "Using multivariable logistic regression models, we found seven independent predictors of PPCs: age ≥70 years, current smoker within 2 months, ASA class ≥2, the presence of airflow limitation, serum albumin <4.0 g/dL, emergency surgery, and cardiac/aortic aneurysm repair/abdominal open surgery." (PMID 25437175, 2014). "Of note, preliminary data already revealed that patients with aortic aneurysm peaked out for absolute concentrations of TNF-α at 18.16 ± 16.44 pg/ml (mean ± SD), an effect that remains visible for albumin-normalized TNF-α levels." (PMID 39501015, 2024). "Indeed, in aortic aneurysms and dissections, no specifically elevated sVEC was observed, considering that the significantly low levels found in carotid stenosis are due to the high plasma albumin concentration." (PMID 39501015, 2024).
asthenia (5 papers, 2017 to 2025). Clinical sign or symptom manifested as debility, or lack or loss of strength and energy. "In a previous multicenter cohort study of older adult males in the United States, a decrease in albumin levels indicated a reduced possibility of improving asthenia." (PMID 37559927, 2023). "The most common adverse events reported were vomiting and a decrease in calcium blood levels (in 50% of all patients), asthenia and activated partial thromboplastin time prolonged (42.9% each), and blood albumin decreased (35.7%)." (PMID 28154921, 2017).
Ataxia (5 papers, 2016 to 2025). Ataxia refers to impaired coordination of voluntary muscle movement. "Blood tests including alpha‐fetoprotein, albumin, cholesterol, lactate/pyruvate, and cytosine‐thymine‐guanine repeats in spinocerebellar ataxia 1, 2, 3, and dentatorubral pallidoluysian atrophy disclosed no abnormalities in both patients." (PMID 32895939, 2021). "Specifically, these adverse effects most commonly included increased serum ALP activity and ALT activity followed by sedation, ataxia, polydipsia, polyuria, polyphagia, euthyroid sick syndrome, hyperactivity, increased serum γ-GT activity, decreased serum albumin and diarrhoea." (PMID 27206489, 2016).
cataract (5 papers, 2009 to 2026). Partial or complete opacity of the crystalline lens of one or both eyes that decreases visual acuity and eventually results in blindness. "We identified 64 proteins, most of which were identified in previous AH proteomic studies of patients with cataracts, in the albumin-depleted fraction." (PMID 21139973, 2010). "Proteins bound to albumin in the aqueous humor of patients with cataracts identified using LC-MS/MS." (PMID 20019884, 2009). "Proteins in the albumin-depleted aqueous humor fraction of patients with cataracts identified with high confidence using LC-MS/MS." (PMID 20019884, 2009).
Cervical lymphadenopathy (5 papers, 2019 to 2024). Enlarged lymph nodes in the neck. "Statistically significant variables including age, cervical lymphadenopathy, NLR, PLR, CRP, TBil, Na+, and ALB were enrolled in multivariate logistic regression analysis." (PMID 33712036, 2021).
chronic rhinosinusitis (5 papers, 2021 to 2025). Chronic form of sinusitis. "The authors also consider it relevant in the future to carry out studies that allow the association of serum albumin levels with the time of evolution of chronic rhinosinusitis, ideally, prospective cohort studies." (PMID 36923165, 2023). "We conducted a literature review on the association of sinusitis with the four variables that compose an NFI formula and found a previous study reported that serum albumin was significantly lower in patients with chronic rhinosinusitis than those without." (PMID 33852653, 2021).
coronary artery calcification (5 papers, 2015 to 2025). Calcification of the coronary artery, used as a measure of coronary atherosclerosis, a risk factor for myocardial infarction. "However, adjusted mediation analyses did not detect any indication of a causal mediation pathway linking the effects of sarcopenic status on coronary artery calcification score, C-reactive protein, serum albumin, or 25(OH) vitamin D levels to MACE outcomes." (PMID 39315011, 2024).
coronary atherosclerosis (5 papers, 2022 to 2026). Atherosclerosis of the coronary vasculature. "Several studies have provided compelling evidence that lower serum albumin concentrations promote the development and progression of coronary atherosclerosis and are associated with poor clinical outcomes in CAD patients." (PMID 38807036, 2024). "As a new inflammatory biomarker, PFAR integrates fibrinogen and albumin levels into a more comprehensive and sensitive indicator of inflammation, oxidative stress, and the consequent coronary atherosclerosis." (PMID 37932710, 2023). "Althoughneutrophil percentage and albumin level have been shown to affect the prognosisof patients with coronary atherosclerosis, NPAR can magnify this change.Clinicians can evaluate the condition more accurately according to NPAR." (PMID 39077142, 2022).
dental caries (5 papers, 2017 to 2023). The decay of a tooth, in which it becomes softened, discolored, and/or porous. "Parket al.17 noted the high CRP/albumin ratio in cases of dental caries and its association with disease for long periods, and thus decreased survival rates." (PMID 37224312, 2023). "Age, sex, smoking habit, probing pocket depth, alveolar bone loss, oral hygiene, number of teeth, leukocytes, haemoglobin, and albumin counts, cancer treatment, the administration of immunosuppressants, worsening of dental caries, and alveolar bone loss after 1–2 years were examined." (PMID 34264046, 2021). "Hence, this study found a significant negative association between salivary albumin and dental caries and a subsequent increase in caries incidence with decreased levels of salivary albumin." (PMID 36553087, 2022).
dependence (5 papers, 2022 to 2025). "However, albumin levels above 3.45 g/dL were found to be significant in terms of not developing steroid dependence, with AUC: 0.73, 79.2% sens." (PMID 41597331, 2025).
dilatation (5 papers, 2015 to 2024). "Previous studies have identified a few risk factors for coronary dilatation or aneurysmal formation, including late IVIG treatment, IVIG unresponsiveness, and several clinical biomarkers, such as serum albumin levels and CRP levels." (PMID 28587647, 2017). "However, the presence of intrapulmonary vascular dilatation was not confirmed with contrasted-enhanced echocardiography or perfusion lung scanning with technetium-99m-labelled macroaggregated albumin." (PMID 31626650, 2019). "Moreover, the patients with normal serum albumin levels did not develop progressive coronary dilatation (P = 3 × 10−4)." (PMID 28587647, 2017).
HCMV infection (5 papers, 2016 to 2024). "Multivariate analysis showed that high-dose glucocorticoid treatment and immunosuppressive agents were independent risk factors for CMV infection, while low albumin and eosinophil levels were also risk factors for CMV infection in UC patients." (PMID 32891125, 2020). "With every 0.1*10^9/L decrease in the peripheral blood eosinophil level or 1 g/L decrease in the serum albumin level, the risk for CMV infection in UC patients increased by 5.21-fold (1/0.192) or 1.19-fold (1/0.839), respectively." (PMID 32891125, 2020). "With every 1 g/L increase in the serum albumin level, the risk of CMV infection in UC patients decreased by 16.1% (1–0.839)." (PMID 32891125, 2020). "The association between fetal HCMV infection and increased sHLA-G expression in amniotic fluid was confirmed calculating the sHLA-G index in comparison with albumin." (PMID 27699182, 2016). "High-dose glucocorticoid and immunosuppressive agent treatment significantly increase the risk of CMV infection, and correcting eosinopenia and low albumin levels may help prevent CMV infection in UC patients." (PMID 32891125, 2020). "A decrease eosinophil and albumin levels were risk factors for CMV infection." (PMID 32891125, 2020). "Conversely, increases in eosinophil and albumin levels were protective factors against CMV infection." (PMID 32891125, 2020). "Further studies are needed to investigate the role of albumin intervention in CMV infection in UC patients." (PMID 32891125, 2020). "Furthermore, patients with CMV infection showed lower serum albumin levels, which was probably due to sever inflammatory process (present as high hsCRP levels) and insufficient intake." (PMID 32891125, 2020). "HCMV infection may inhibit HBV proliferation and reduce liver injury, while EBV infection possibly influenced liver function, as EBV-infected patients had lower albumin levels and higher Child-Pugh scores." (PMID 30445927, 2018). "However, the effect of treatment targeting at increasing albumin in CMV infection has not been fully illustrate." (PMID 32891125, 2020).